SLC4A11 (solute carrier family 4 member 11)
Diseases named in the same sentence as SLC4A11 in open-access papers (continued):
Sharing a sentence is not in itself a finding about the gene and the disease.
ovarian carcinoma (6 papers, 2017 to 2025). A malignant neoplasm originating from the surface ovarian epithelium. "Of the seven ovarian cancer biomarker genes considered, SLC4A11 had the highest percentage of mutations." (PMID 40563515, 2025). "High expression of the SLC4A11 gene is associated with poorer overall survival in patients with ovarian cancer, particularly in those with HGSOC." (PMID 41465326, 2025). "In ovarian cancer, high SLC4A11 expression was associated with worse overall survival." (PMID 40563515, 2025). "Moreover, high expression of SLC4A11 appears to be a risk factor in ovarian cancer and a recent study uncovered increased SLC4A11 expression associated with poor outcomes in colon cancer." (PMID 35053313, 2022). "This means that ovarian cancer patients with higher levels of SLC4A11 tend to have a lower chance of surviving their cancer." (PMID 41465326, 2025). "SLC4A11 locates in chromosome 20p in the human genome, a region with a relatively high frequency of genetic amplification in ovarian cancer." (PMID 29091960, 2017). "Results showed that SLC4A11 was upregulated in ovarian cancer compared with normal ovarian epithelial tissues." (PMID 29091960, 2017). "In this study, we aimed to examine the expression of SLC4A11 in ovarian cancer and in normal ovarian tissues, its prognostic value and the possible mechanism of its dysregulation." (PMID 29091960, 2017). "By using deep sequencing data in TCGA-OV, we found that 320 out of 578 ovarian cancer cases had SLC4A11 amplification." (PMID 29091960, 2017). "In this study, we examined the expression of SLC4A11 in ovarian cancer/normal ovarian tissues and further assessed its prognostic value and the possible mechanism of its dysregulation." (PMID 29091960, 2017). "By using the results from Illumina 27k methylation array, we found that the group with high DNA methylation had significantly lower SLC4A11 expression, suggesting that epigenetic alterations also contribute to SLC4A11 upregulation in ovarian cancer." (PMID 29091960, 2017). "In this study, we found that SLC4A11 expression is significantly upregulated in ovarian cancer tissues than in normal tissues." (PMID 29091960, 2017). "Therefore, we infer that SLC4A11 upregulation is an important mechanism leading to malignant cellular behaviors in ovarian cancer." (PMID 29091960, 2017). "Therefore, DNA amplification is one important mechanism of upregulated SLC4A11 in ovarian cancer." (PMID 29091960, 2017). "Using data from TCGA-OV, we compared SLC4A11 expression in ovarian cancer patients with or without lymphatic invasion." (PMID 29091960, 2017).
corneal diseases (5 papers, 2013 to 2023). "Understanding SLC4A11 function and substrate transport activities is important because mutations in SLC4A11 have been shown to cause corneal diseases like congenital hereditary endothelial dystrophy." (PMID 35903773, 2022). "Most previous studies have focused on the link between SLC4A11 mutations and human corneal disorders." (PMID 31833218, 2019). "Human SLC4A11 has been reported to mediate water movement uncoupled from solute flux, similar to AQP proteins, which might explain the human corneal diseases caused by SLC4A11 mutations." (PMID 31833218, 2019). "Data here provide an explanation for the corneal diseases caused by SLC4A11 defects." (PMID 23813972, 2013). "In addition to corneal disease, SLC4A11 mutations also cause sensorineuronal deafness (Harboyan Syndrome) due to defects in the inner ear's stria vascularis, the structure responsible for maintenance of the composition of the inner ear's endolymph." (PMID 23813972, 2013). "When comparing the expression levels of the two clinically important genes known for corneal diseases (i.e., Slc4a11 and Slc4a4), the expression of Slc4a11 was approximately three times greater than that of Slc4a4 (3.4±0.3; p=0.004)." (PMID 23734078, 2013). "Accordingly, borate transport by SLC4A11 does not provide an obvious explanation for the corneal diseases arising from SLC4A11 mutations." (PMID 23813972, 2013).
Corneal Dystrophy and Perceptive Deafness (3 papers, 2008 to 2023). "Mutations in SLC4A11 are described in Harboyan syndrome, also known as Corneal Dystrophy and Perceptive Deafness (CDPD; OMIM 217400), which is characterized as CHED2 with hearing loss." (PMID 21203343, 2010). "The study of 3 consanguineous and 3 nonconsanguineous families with Harboyan syndrome revealed homozygosity or compound heterozygosity, respectively, for SLC4A11 mutations in Harboyan patients, indicating that CHED2 and Harboyan syndrome are allelic disorders." (PMID 18922146, 2008).
Fuchs' endothelial dystrophy (3 papers, 2008 to 2018). Fuchs endothelial corneal dystrophy (FECD) is the most frequent form of posterior corneal dystrophy and is characterized by excrescences on a thickened Descemet membrane (corneal guttae), generalized corneal edema, with gradually decreased visual acuity. "Multiple genetic loci have been linked to Fuchs' endothelial dystrophy, including but not limited to TCF4, COL8A2, SLC4A11, ZEB1 and LOXHD1." (PMID 29685994, 2018). "Comparative SAGE analysis of gene expression profiles showed that SLC4A11 is downregulated in Fuchs endothelial dystrophy." (PMID 18922146, 2008).
hearing loss (3 papers, 2015 to 2024). "Variants in SLC4A11 caused congenital hereditary endothelial dystrophy (CHED) or Harboyan syndrome (CHED co-existing with hearing impairment)." (PMID 36902444, 2023).
macular corneal dystrophies (3 papers, 2019 to 2022). "For example, direct correlations have been established between mutations in CHST6, UBIAD1, SLC4A11, PIKFYVE, TACSTD2, and DCN with macular corneal dystrophies (MCD), Schnyder CD, congenital hereditary endothelial dystrophy, fleck CD, gelatinous drop-like CD, and congenital stromal CD, respectively." (PMID 31555324, 2019).
congenital glaucoma (2 papers, 2023 to 2025). "Homozygous missense variants cause approximately half of SLC4A11-related disease, and both families with congenital glaucoma whose variants have been reported had homozygous missense mutations; these were c.1343G>A p.(Gly448Asp) and c.2024A>C p.(Glu657Ala), respectively." (PMID 41011222, 2025).
corneal opacities (2 papers, 2024). "In the genetic examination, the suspected variant genes of this child associated with corneal opacities include SLC4A11 and PLG." (PMID 39669368, 2024).
edema (2 papers, 2013 to 2021). An abnormal accumulation of fluid beneath the skin, or in one or more cavities of the body. "Slc4a11−/− mice manifest corneal oedema and distorted endothelial cells, consistent with loss of a water-flux." (PMID 23813972, 2013). "The conventional Slc4a11 knockout (KO) shows significant corneal edema at eye opening, a fact that complicates the study of the initial events leading to edema." (PMID 34190974, 2021). "The conventional Slc4a11 KO shows progressive corneal edema that is apparent at eye opening, altered endothelial morphology, significant endothelial oxidative damage, and mitochondrial dysfunction, with eventual cell loss and diminished cell density." (PMID 34190974, 2021). "The inducible Slc4a11 KO will provide opportunities to examine the very earliest events of cell and tissue dysfunction that lead to gene expression changes, the development of corneal edema, and eventual apoptosis." (PMID 34190974, 2021).
hepatocellular carcinoma (2 papers, 2024 to 2025). A malignant tumor that arises from hepatocytes. "Increased expression of SLC4A11 has been demonstrated in several cancer types: lung squamous cell carcinoma, ovarian adenocarcinoma, hepatocellular carcinoma, gastric cancer, and colorectal cancer." (PMID 40563515, 2025). "Additionally, quantitative PCR studies have shown increased SLC4A11 expression in hepatocellular carcinoma (HCC) and gastric cancer." (PMID 40563515, 2025).
keratoconus (2 papers, 2018 to 2023). A degenerative, structural disorder of the eye, characterized by a cone-shaped protrusion of the cornea. "SLC4A11 (OMIM: #610206) is directly related to keratoconus, as it codes for a bicarbonate and sodium transporter that regulates oxidative stress in the corneal endothelium by enhancing antioxidant defenses." (PMID 37895187, 2023).
mastitis (2 papers, 2016 to 2025). Inflammation of breast tissue during lactation or postpartum due to an obstructed duct or infection. "To elucidate the potential mechanisms underlying ammonia’s ability to suppress mastitis progression, we focused on the ammonia transport-related gene SLC4A11." (PMID 40370468, 2025). "A total of 28 genes (e.g., CXCL14, KIT, and SLC4A11) were suggested as the most promising candidates associated with S. aureus-induced mastitis for follow-up functional studies." (PMID 28083515, 2016). "Additionally, SLC4A11 has been identified as a candidate gene associated with resistance to mastitis in dairy cows, suggesting that genetic variations in this gene could influence an animal’s susceptibility to the disease." (PMID 40370468, 2025). "Our study adds to this body of work by demonstrating that ammonia, through its interaction with Slc4a11, can inhibit the activity of pro-inflammatory T cells, providing a means to dampen the inflammatory response and protect against tissue damage associated with mastitis." (PMID 40370468, 2025). "This indicates that Slc4a11 plays a crucial role in modulating T cell responses and thereby influencing the inflammatory process in LPS-induced mastitis." (PMID 40370468, 2025). "Knockdown of the ammonia transporter Slc4a11 in T cells exacerbated mastitis, suggesting that Slc4a11 regulates T cell activity and inflammation during the progression of mastitis." (PMID 40370468, 2025). "While our study provides novel insights into the role of ammonia and Slc4a11 in mastitis, there are limitations that warrant further investigation." (PMID 40370468, 2025). "In summary, these findings highlight the critical role of ammonia and its transporter Slc4a11 in LPS-induced mastitis, providing potential therapeutic targets for future interventions." (PMID 40370468, 2025). "The modulation of ammonia levels and the targeting of Slc4a11 offer a potential therapeutic strategy for the treatment of mastitis." (PMID 40370468, 2025). "HE staining demonstrated that deletion of SLC4A11 in T cells led to a significant exacerbation of mastitis severity." (PMID 40370468, 2025). "The precise mechanisms by which SLC4A11 operates in mastitis are not fully understood but likely involve multiple pathways." (PMID 40370468, 2025). "Integrated analysis with QTL database further suggested 28 genes (e.g., CXCL14, KIT, and SLC4A11) as candidates of bovine mastitis." (PMID 28083515, 2016). "The findings suggest that targeting the ammonia-Slc4a11 axis may offer a promising approach for the management of mastitis, warranting further research into its therapeutic potential." (PMID 40370468, 2025). "In the context of mastitis—an inflammatory condition of the mammary glands—SLC4A11 may contribute to the pathogenesis by influencing the transport of these ions, thereby affecting cellular pH and potentially modulating the inflammatory response." (PMID 40370468, 2025). "In conditions like mastitis, where inflammation is heightened, the role of SLC4A11 in managing ammonia levels could be particularly crucial." (PMID 40370468, 2025). "This suggests that SLC4A11 could be a key player in the modulation of T cell activity in mastitis." (PMID 40370468, 2025). "To determine whether Slc4a11 regulates the progression of mastitis through modulation of T cells, we employed CRISPR-Cas9 technology to knock down Slc4a11 expression specifically in T cells." (PMID 40370468, 2025).
serous ovarian carcinoma (2 papers, 2017 to 2021). "Based on these findings, we infer that high SLC4A11 expression is an independent predictor for poor OS in grade 3/4 serous ovarian cancer." (PMID 29091960, 2017). "In comparison, the serous ovarian cancer tissues usually had low to medium SLC4A11 staining in both cytoplasma and cell membrane." (PMID 29091960, 2017). "Based on findings above, we infer that high SLC4A11 expression is an independent predictor for poor OS in grade 3/4 serous ovarian cancer." (PMID 29091960, 2017). "Here we may infer that high SLC4A11 expression can be a potential predictor for poor overall survival in low-grade serous ovarian carcinoma." (PMID 34062972, 2021). "In patients with primary serous ovarian cancer in TCGA-OV, the cases with lymphatic invasion (N = 133) had significantly higher SLC4A11 expression than those without lymphatic invasion (N = 77) (p = 0.0069)." (PMID 29091960, 2017).
-dependent (1 paper, 2025). "Given the established association of SLC4A11 mutations with CHED and Harboyan syndrome, and its potential involvement in glutamine-dependent cancers, investigating SLC4A11’s role in disease pathogenesis is important for medical genetics." (PMID 40563515, 2025).
albinism (1 paper, 2020). A congenital disorder characterized by partial or complete absence of melanin pigment in the eyes, hair, or skin. "The genes identified for MAC were KMT2D, MAB2IL2, ALDH1A3; ASDA were KERA, PAX6, MYOC, TGFBI, and SLC4A11; congenital cataract were CRYBB2, EPHA2, HSF4 and BCOR; infantile nystagmus were CACNA1A and FRMD7; and albinism were OCA2, GPR143, HPS6 and SLC38A8." (PMID 32830442, 2020).
colorectal cancer (1 paper, 2025). A primary or metastatic malignant neoplasm that affects the colon or rectum. "Elevated SLC4A11 expression has also been detected in colorectal cancer samples using various methods." (PMID 40563515, 2025). "IHC analyses have confirmed SLC4A11 protein expression in ovarian, hepatocellular, gastric, and colorectal cancer tissues." (PMID 40563515, 2025).
deafness (1 paper, 2025). An inherited or acquired condition characterized by the complete loss of the ability to hear from one or both ears. "In addition to GAPDH and TCF4, SLC4A11 was chosen as a comparison gene because of its confirmed association with congenital hereditary endothelial dystrophy (CHED) accompanied by perceptive deafness." (PMID 40244234, 2025).
endometrioid adenocarcinoma (1 paper, 2025). An adenocarcinoma characterized by the presence of malignant glandular epithelial cells resembling endometrial cells. "Mutations in the SLC4A11 gene have also been shown to be associated with endometrioid adenocarcinoma." (PMID 40563515, 2025). "However, the functional role of SLC4A11 in the development of endometrioid adenocarcinoma remains the subject of further research." (PMID 40563515, 2025).
gastric cancer (1 paper, 2025). A primary or metastatic malignant neoplasm involving the stomach. "Increased expression of SLC4A11 correlates with disease progression and poor prognosis in patients with gastric cancer." (PMID 40563515, 2025).
glaucoma (1 paper, 2024). Increased pressure in the eyeball due to obstruction of the outflow of aqueous humor. "All variants detected were in genes previously associated with glaucoma and are “Green” in the glaucoma panel of PanelApp except SLC4A11 and COL18A1 which are not in the glaucoma panel, but are rated “Green” in the corneal abnormalities (v1.12) and structural eye disease (v3.2) panels, respectively." (PMID 38755526, 2024). "However, the involvement of SLC4A11 and COL18A1 with glaucoma cases has been reported in the literature." (PMID 38755526, 2024).
Microcornea (1 paper, 2012). A congenital abnormality of the cornea in which the cornea and the anterior segment of the eye are smaller than normal. "While specific corneal functions of many of these solute carrier family members are not known, it is noteworthy that mutations in SLC4A11 and SLC16A12 are associated with congenital hereditary endothelial dystrophy (CHED) and microcornea, respectively." (PMID 23024760, 2012).
mucinous adenocarcinoma (1 paper, 2021). An invasive adenocarcinoma composed of malignant glandular cells which contain intracytoplasmic mucin. "SLC4A11 was expressed in high-grade serous carcinoma, low-grade serous carcinoma, mucinous adenocarcinoma and metastatic serous carcinoma." (PMID 34062972, 2021).
ovarian adenocarcinoma (1 paper, 2025). An adenocarcinoma that arises from the ovary. "More recent reanalysis of hybridization microarray data demonstrated significant upregulation of SLC4A11 in ovarian adenocarcinoma compared to normal ovarian epithelium." (PMID 40563515, 2025).
ovarian tumors (1 paper, 2025). "When SLC4A11 was first described, the GeneBank database mentioned the discovery of SLC4A11 cDNA fragments, expressed sequence tags (ESTs), corresponding to a sample of five pooled ovarian tumors and a sample of squamous cell carcinoma of the lung." (PMID 40563515, 2025).
Polyuria (1 paper, 2019). An increased rate of urine production. "In Slc4a11 knockout mice, sodium chloride crystals form in the cornea and polyuria is associated with an increased loss of NaCl and hypo‐osmolarity of the urine." (PMID 31833218, 2019).
psoriasis (1 paper, 2016). An autoimmune condition characterized by red, well-delineated plaques with silvery scales that are usually on the extensor surfaces and scalp. "Of the five genes (BATF2, HRNR, SIGLEC1, SLC4A11, CXCL10) uniquely identified by multiDE (with Bonferroni adjustment), four were found to be closely related to psoriasis." (PMID 27334001, 2016).
renal agenesis (1 paper, 2025). Renal agenesis (RA) is a form of renal tract malformation characterized by the complete absence of development of one or both kidneys (unilateral RA or bilateral RA respectively), accompanied by absent ureter(s). "Other genetic causes of renal agenesis were not investigated in this case, so an association between SLC4A11 mutation and renal agenesis is inconclusive." (PMID 40563515, 2025).
uterine corpus endometrioid carcinoma (1 paper, 2022). "Out of 30 gynaecological cancer amino acid changes, only 1 amino acid change, at R831C/R804C, has detected the structural damage of the protein SLC4A11, therefore, we modelled this protein (SLC4A11) with SNP at R831C/R804C in uterine corpus endometrioid carcinoma." (PMID 35163645, 2022).